APOBEC3A (apolipoprotein B mRNA editing enzyme catalytic subunit 3A)
Diseases named in the same sentence as APOBEC3A in open-access papers (continued):
Sharing a sentence is not in itself a finding about the gene and the disease.
bladder cancer (12 papers, 2018 to 2025). "The case of the APOBEC3A gene-associated variant further highlights this complex nature, as it shows a strong protective effect against bladder cancer but a significant increased risk for BC." (PMID 41463216, 2025). "Specifically, in bladder cancer, we observed that germline APOBEC3A/B deletion was significantly associated with decreased APOBEC-mutational signature (P = 1.7 × 10− 3)." (PMID 31533728, 2019). "To recreate this dynamic pattern, we employed a doxycycline-inducible APOBEC3A system in the 5637 bladder cancer cell line, a well-characterized basal-type bladder cancer cell line." (PMID 41278855, 2025). "Expression of two enzymes of the family APOBEC3A and APOBEC3B is associated with high TMB in bladder carcinomas." (PMID 35323317, 2022). "The APOBEC3A and APOBEC3B cytosine deaminases are the main mutators of bladder cancer genomes (evidenced as COSMIC SBS2 and SBS13 mutational signatures in 93% of bladder tumours) and therefore account for most of the neoantigen load in bladder tumours." (PMID 36358715, 2022). "Recently, Middlebrooks and colleagues analyzed the expression level of the APOBEC3A/B deletion isoform as a proxy to evaluate the association between germline APOBEC3A/B deletion and APOBEC-mutational signature in breast and bladder cancer." (PMID 31533728, 2019). "Expression of APOBEC3A and APOBEC3B were the only APOBEC enzymes that directly correlate with the total mutation burden in bladder cancer." (PMID 29435122, 2018). "Many earlier studies reported elevated expression and activity of APOBEC3B and APOBEC3A in bladder cancer and of APOBEC3B in head and neck cancer patients." (PMID 29642934, 2018). "To confirm that APOBEC3A’s DNA-damaging effects depend on its deaminase activity across different bladder cancer subtypes, we compared wild-type and deaminase-inactive APOBEC3A variants in the RT112/84 cells, a luminal cell line with low baseline genome instability." (PMID 41278855, 2025). "This is consistent with high propensity towards APOBEC3A mutagenesis in bladder cancer." (PMID 35015788, 2022). "We demonstrate that bladder tumors not enriched for APOBEC mutagenesis frequently harbor mutations in FGFR3 or the RAS family of oncogenes, and we also demonstrate that APOBEC3A is expressed at significantly higher levels in the basal subtype of bladder cancer, compared to other subtypes." (PMID 29435122, 2018). "Regulation of APOBEC enzymes remains unclear, but expression of APOBEC3A and APOBEC3B can be induced in bladder cancer cell lines by the DNA-damaging agent bleomycin, as well as by an interferon response." (PMID 29435122, 2018). "Expression of APOBEC3A and APOBEC3B correlates with overall mutation load in bladder cancer, regardless of molecular subtype." (PMID 29435122, 2018). "While the roles of APOBEC3A and APOBEC3B in bladder cancer have not been functionally explored, transgenic overexpression of APOBEC3G in a BBN-induced carcinogen mouse model of bladder cancer has documented that APOBEC3G can shorten survival as well as drive genomic instability." (PMID 41390483, 2025).
HIV-1 infection (11 papers, 2011 to 2022). The type species of lentivirus and the etiologic agent of acquired immunodeficiency syndrome (AIDS). "Induction of APOBEC3A by ALFQ decreased permissiveness to HIV-1 infection, while knockdown of APOBEC3A with APOBEC3AsiRNA resulted in a significant loss in the restriction of HIV-1 infectivity." (PMID 35534646, 2022). "Interestingly, APOBEC3A expression levels have been linked to myeloid cell restriction of HIV-1 infection." (PMID 24782834, 2014). "Here, we demonstrate that the Army Liposome Formulation containing MPLA, and QS-21 (ALFQ) activated MDM that are normally permissive to HIV-1 infection to generate a proinflammatory environment and upregulated anti-viral factors notably APOBEC3A." (PMID 35534646, 2022). "Silencing of APOBEC3A gene in monocytes render them permissive to HIV-1 infection whereas, induction of APOBEC3A in MDM render them more resistant to HIV-1 infection." (PMID 35534646, 2022). "For example, APOBEC3A is highly expressed in myeloid-lineage cells and interacts with Vpx, leading to its degradation, which correlates with increased HIV-1 infection in primary monocytes." (PMID 23231760, 2012). "Around the time SAMHD1 was identified, it was reported that another host restriction factor, APOBEC3A, inhibits HIV-1 infection of MDMs, and that APOBEC3A is degraded by Vpx." (PMID 22908011, 2012). "Thus, our study demonstrates that the induction of APOBEC3A by ALFQ restricts HIV-1 infection in ALFQ-treated MDM." (PMID 35534646, 2022). "Conversely, APOBEC3A can restrict infection directly in the target cells where it is endogenously expressed, and it was indeed identified as a specific inhibitor of the early phases of HIV-1 infection in macrophages." (PMID 33072075, 2020). "However, the precise contribution of APOBEC3A to the resistance of HIV-1 infection in myeloid cells is difficult to evaluate, as SAMHD1 imposes a strong barrier to infection in these cells and is counteracted by Vpx." (PMID 24782834, 2014). "Further work will be required to address the exact role of APOBEC3A in the IFN-induced block to HIV-1 infection, and to determine whether Vpx is counteracting additional IFN-induced anti-HIV-1 factors in myeloid cells." (PMID 24782834, 2014). "Furthermore, APOBEC3A has been suggested to be a specific inhibitor of the early phases of HIV-1 infection in myeloid cells, likely functioning together with SAMHD1 to block HIV-1 replication with different mechanisms." (PMID 24523981, 2013). "Moreover, APOBEC3A has been recently reported as a inhibitor of HIV-1 infection in myeloid cells." (PMID 22570689, 2012). "In monocytes, APOBEC3A, together with APOBEC3G, represents a potent innate barrier to HIV-1 infection, which diminishes during differentiation to macrophages, resulting in a more susceptible population of target cells." (PMID 33072075, 2020).
cervical cancer (6 papers, 2020 to 2024). A primary or metastatic malignant neoplasm involving the cervix. "APOBEC3A is significantly overexpressed in cervical cancer, and higher expression of APOBEC3A is associated with better outcomes." (PMID 38021159, 2023). "The association between the APOBEC3A polymorphism and cervical cancer needs to be further investigated." (PMID 38021159, 2023). "Second, APOBEC3A has potent deamination activity in cervical cancer cell lines and is strongly associated with mutational burden in cervical cancers." (PMID 38021159, 2023). "Higher expression of APOBEC3A and UNG in cervical cancer was associated with better outcomes (P = 0.039 and P = 0.019, respectively), according to TCGA." (PMID 38021159, 2023). "Poorly differentiated cervical cancer tissues had higher APOBEC3A expression than moderately well-differentiated cervical cancer (P < 0.001)." (PMID 38021159, 2023). "The APOBEC3A to UNG expression level ratio was significantly higher in cervical cancer than in intraepithelial lesion tissues (P = 0.002)." (PMID 38021159, 2023). "APOBEC3A inhibits cell migration and invasion, arrests cells in S-phase, promotes cervical cancer cell apoptosis by inducing DNA damage that exceeds cellular tolerance, and inhibits several cancer-associated signaling pathways." (PMID 38021159, 2023). "Our data support that HPV infection and higher inflammation levels in cervical cancer promote APOBEC3A expression." (PMID 38021159, 2023). "Our study demonstrated that ectopically expressed APOBEC3A caused cell-cycle arrest in the S-phase and downregulated the G2 stage, suggesting that APOBEC3A inhibits the ATR-Chk1 pathway in cervical cancer cells, leading to cell death." (PMID 38021159, 2023). "We focused on the effects of APOBEC3A on the biological behavior of cervical cancer cells and the relationship between APOBEC3A and outcomes." (PMID 38021159, 2023). "According to GSE7803, APOBEC3A expression was significantly higher in cervical cancer than in intraepithelial lesion tissues (P = 0.001)." (PMID 38021159, 2023). "APOBEC3A and pro-inflammatory factors IL-6 and NF-κB were more highly expressed in cervical cancer tissues than in adjacent normal tissues." (PMID 38021159, 2023). "APOBEC3A exerts anti-tumor effects in cervical cancer is partly because the APOBEC3A-mediated DNA damage exceeds the cellular tolerance, thus promoting cancer cell apoptosis." (PMID 38021159, 2023). "The analysis revealed that the transcriptional downregulation of APOBEC3A expression was associated with poor DFS and OS in human cervical cancers (P‐value = .007 and 0.054, log‐rank test)." (PMID 33017516, 2020). "Elevated POSTN and reduced APOBEC3A at transcription level correlated with unfavorable cervical cancer clinical outcomes." (PMID 33017516, 2020). "We used RNA-Seq analysis to explore the pathways for APOBEC3A action in cervical cancer cells." (PMID 38021159, 2023). "However, our results indicated that although APOBEC3A is significantly upregulated in cancer tissues, it exerts an anti-cancer effect and correlates with better outcomes in cervical cancer." (PMID 38021159, 2023). "Here, we presented and validated a hypothesis that may clarify this contradiction: Factors including HPV infection and high inflammation levels promote the expression of APOBEC3A in cervical cancer." (PMID 38021159, 2023). "Therefore, we explored the APOBEC3A expression pattern and its effects on biological behaviors such as proliferation, apoptosis, invasion, and migration in cervical cancer." (PMID 38021159, 2023). "However, the somatic mutagenicity and antiviral effects of APOBEC3A are also essential for the occurrence and development of cervical cancer." (PMID 38021159, 2023). "APOBEC3A is a tumor suppressor whose overexpression induces apoptosis in cervical cancer." (PMID 38021159, 2023). "Moreover, APOBEC3A has been shown to be a probable driver of cervical cancer pathogenesis." (PMID 38976757, 2024).
cervical cancer (continued). "However, the role of APOBEC3A in cervical cancer remains to be clarified." (PMID 38021159, 2023). "High APOBEC3A expression was associated with advanced International Federation of Gynecology and Obstetrics (FIGO) staging (χ2 = 12.931, P = 0.002), lymph node metastasis (χ2 = 4.156, P = 0.041), and pathological histological hypofractionation (χ2 = 5.911, P = 0.015) in cervical cancer patients." (PMID 38021159, 2023). "However, the roles of APOBEC3A in cervical cancer are unclear." (PMID 38021159, 2023). "Therefore, APOBEC3A conversely exerts an anti-cancer effect in cervical cancer." (PMID 38021159, 2023). "The relationship between APOBEC3A and HPV in cervical cancer development remains to be further investigated." (PMID 38021159, 2023). "APOBEC3A and UNG expression levels were significantly higher in cervical cancer than in adjacent normal tissues, according to TCGA and GTEx (P < 0.001)." (PMID 38021159, 2023). "We found that the LOXL2-interference resulted in an increase in APOBEC3A, APOBEC3B, APOBEC3D, and APOBEC3G protein levels in the cervical cancer cells." (PMID 32211324, 2020). "However, the ratio of APOBEC3A to UNG is also increased in tumor tissues, suggesting that the DNA damage-repair balance is disturbed in cervical cancer." (PMID 38021159, 2023). "Therefore, we also integrated the APOBEC family (APOBEC1 APOBEC3A, APOBEC3B, APOBEC3C, APOBEC3D, APOBEC3F, APOBEC3G, and APOBEC3H) mRNA expression of 176 core-set cervical carcinoma samples for multiplatform integrative analyses." (PMID 32211324, 2020).
COVID-19 (6 papers, 2022 to 2025). A disease caused by infection with severe acute respiratory syndrome coronavirus 2. "Investigations have demonstrated that another gene upregulated in COVID-19 patients, namely APOBEC3A, is a critical factor in the inhibition of coronaviruses, by restricting the RNA virus replication." (PMID 41168347, 2025). "The identification of DEGs such as OAS1, APOBEC3A, and IFI44, as well as genes associated with immune responses, highlights the robust activation of antiviral pathways during COVID-19." (PMID 41168347, 2025). "APOBEC3A (also called A3A) is one of the most down-regulated genes in patients with severe COVID-19 condition." (PMID 37347079, 2023). "In our study, we demonstrated that a SNP of APOBEC3A located in its promoter is only polymorphic in AFR population and also displays suggestive association with COVID-19 hospitalization." (PMID 38105291, 2023). "Genes in this pathway, AICDA, CDADC1, CDA and APOBEC3D, were regulated in opposite directions (only AICDA was statistically significantly downregulated in SLE and CDA up in COVID-19), while APOBEC3A and APOBEC3B were significantly upregulated in COVID-19, but not SLE." (PMID 38302132, 2024). "Furthermore, APOBEC3A/B/G/H were upregulated upon SARS-CoV-2 infection in blood samples of COVID-19 patients." (PMID 38105291, 2023). "Thus, it is warrant for further replication of the association of 3 prioritized APOBEC3 eQTLs in association with COVID-19 hospitalization and determine it is APOBEC3A but not other APOBEC3 proteins involved in the generation of high transmissible SARS-CoV-2 in AFR populations." (PMID 38105291, 2023). "We found a high expression of APOBEC3A, APOBEC3B, APOBEC3C, APOBEC3D, APOBEC3F, APOBEC3G and APOBEC3H in the classical, intermediate monocytes and NK cells of the COVID-19 patients compared to the healthy or recovered individuals." (PMID 36532041, 2022).
bladder tumor (4 papers, 2018 to 2025). "To determine whether APOBEC3A or APOBEC3B was the predominant deaminase, we compared our BKPyV infection models of urothelial carcinogenesis and patient bladder tumor data to a Hap1 cell line model [with overexpression of APOBEC3A or APOBEC3B in isolation]." (PMID 41337590, 2025).
colon cancer (4 papers, 2021 to 2023). "In a previous study on the same population (Norwegians), we found the APOBEC3A/B deletion not to be associated with reduced risk of any of the four major cancer types, breast, prostate, lung- or colon cancer, in overall assessments." (PMID 34873230, 2021). "However, our data show that certain APOBECs (e.g. APOBEC3A, APOBEC3C, APOBEC3D, etc.)are highly expressed in CYT-high colon tumors, providing evidence of their involvement in them." (PMID 34316699, 2021).
ovarian carcinoma (4 papers, 2021 to 2025). A malignant neoplasm originating from the surface ovarian epithelium. "We observed an association between APOBEC3A/B status and reduced risk for ovarian cancer (OR = 0.75; CI = 0.61–0.91; p = 0.003) applying the dominant model." (PMID 34873230, 2021). "APOBEC3A-mediated editing is also induced by IFN-1 exposure in tumor-associated macrophages isolated from ovarian cancer-related ascites fluid, pointing to a wide role for APOBEC3A in macrophages." (PMID 33483601, 2021). "In the present study, we performed a case–control study in a large Norwegian hospital-based sample set and previously analysed population-based controls, in order to assess the potential association between the APOBEC3A/B deletion variant and risk of ovarian cancer." (PMID 34873230, 2021). "We found that APOBEC3A, an innate immune enzyme involved in virus restriction, acts abnormally in ovarian cancer cells to promote metastasis." (PMID 40059825, 2025). "We genotyped the APOBEC3A/B deletion in hospital-based samples of 1398 Norwegian epithelial ovarian cancer patients without detected BRCA1/2 germline mutations and compared to 1,918 healthy female controls, to assess the potential cancer risk associated with the deletion." (PMID 34873230, 2021).
head and neck cancer (3 papers, 2018 to 2025). A primary or metastatic malignant neoplasm affecting the head and neck. "Therefore, both high levels of APOBEC3B and APOBEC3A and low levels of FHIT expression may influence APOBEC mutagenesis in the head and neck cancer." (PMID 29642934, 2018).
hepatocellular carcinoma (3 papers, 2017 to 2023). A malignant tumor that arises from hepatocytes. "To explore the underlying mechanism of APOBEC3A in lipid metabolism regulation, we constructed an in vitro model of HepG2 (HepG2APOBEC3AOE), a human hepatocellular carcinoma cell line overexpressing APOBEC3A." (PMID 35651912, 2022).
lung adenocarcinoma (3 papers, 2019 to 2025). A carcinoma that arises from the lung and is characterized by the presence of malignant glandular epithelial cells. "In this regard, APOBEC3B (but not APOBEC3A) expression has been recently positively associated with interferon inducible genes expression in lung adenocarcinoma." (PMID 33049910, 2020).
multiple myeloma (3 papers, 2018 to 2022). "Increased expression and activity of both APOBEC3A and APOBEC3B were also reported in multiple myeloma patients, most commonly in those with the t(14:16) translocation, which was associated with poor survival." (PMID 29642934, 2018).
pancreatic cancer (3 papers, 2014 to 2022). "As expected, we observed that germline APOBEC3A/B deletion was significantly associated with decreased expression levels of the isoform uc003awo (APOBEC3B) across all cancer types at P < 0.05, except for pancreas cancer with a P = 0.14." (PMID 31533728, 2019). "Real-time PCR assay showed that APOBEC3A and APOBEC3B were underexpressed in pancreatic cancer tissues than in morphologically normal operative margin tissues." (PMID 25502777, 2014). "However, preliminary data suggest that APOBEC3A activity may result in widespread genomic instability through a non-deaminase dependent mechanism, in a mouse model of pancreatic cancer, suggesting the possibility of novel therapeutics for pancreatic cancer." (PMID 35597990, 2022).
renal cell carcinoma (3 papers, 2018 to 2023). "APOBEC3A functional polymorphisms increase APOBEC3A expression levels and significantly decrease the risk of renal cell carcinoma and biliary tract cancers." (PMID 38021159, 2023). "The functional polymorphisms that increased the expression of APOBEC3A significantly decreased the risk of renal cell carcinoma (RCC)." (PMID 34880864, 2021). "These correlation results suggest a strong contribution of REV1, UNG, and possibly APOBEC3A to overall mutagenesis in sarcoma, melanoma, and renal cell carcinoma, respectively." (PMID 29642934, 2018).
urothelial carcinoma (3 papers, 2022 to 2025). A malignant neoplasm derived from the transitional epithelium of the urinary tract (urinary bladder, ureter, urethra, or renal pelvis). "Furthermore, individuals with higher APOBEC3A/B mutation rates may have a higher risk of developing urothelial carcinoma subsequent to PyVAN, due to the mutagenic effect of APOBEC enzymes on the host genome." (PMID 36146883, 2022). "Crucially, we demonstrate that inhibiting Polθ in urothelial carcinoma cells with APOBEC3A activity induces synthetic lethality in vitro and in vivo." (PMID 41278855, 2025). "Recent studies increasingly implicate APOBEC3A as a key driver of mutagenesis and therapy resistance in several cancers, including urothelial carcinoma." (PMID 41278855, 2025). "Our results demonstrate that mouse Apobec3 and human APOBEC3A promote squamous differentiation in urothelial carcinoma and that this trans-differentiation phenotype is mediated through IL-1α signaling, a target of FDA approved therapies for rheumatologic disease." (PMID 41390483, 2025). "We show that APOBEC3A-induced DSBs are repaired by error-prone TMEJ, contributing to chromosomal instability in patients with urothelial carcinoma." (PMID 41278855, 2025).